ALAS2 (5'-aminolevulinate synthase 2)
Description:
Catalyzes the pyridoxal 5'-phosphate (PLP)-dependent condensation of succinyl-CoA and glycine to form aminolevulinic acid (ALA), with CoA and CO2 as by-products. Contributes significantly to heme formation during erythropoiesis. [Isoform 3]: Catalyzes the pyridoxal 5'-phosphate (PLP)- dependent condensation of succinyl-CoA and glycine to form aminolevulinic acid (ALA), with CoA and CO2 as by-products. Catalytic activity is 75-85% of isoform 1 activity. [Isoform 4]: Catalyzes the pyridoxal 5'-phosphate (PLP)- dependent condensation of succinyl-CoA and glycine to form aminolevulinic acid (ALA), with CoA and CO2 as by-products. Catalytic activity is 65-75% of isoform 1 activity.
Synonyms: ALAS-E; ALASE; ASB; ANH1; SIDBA1; XLDPP; XLEPP; XLSA
Tractability: Small molecule: a structure with a bound ligand is known. Antibody: UniProt places it where antibodies can reach, with high confidence. PROTAC: ubiquitination databases record sites on it.
Gene: Protein-coding gene on chromosome X (55,009,055 to 55,030,986, reverse strand). Ensembl gene ENSG00000158578.
Subcellular location: Mitochondrion inner membrane; Mitochondrion inner membrane (Isoform 4)
Pathways (Reactome):
Metabolism: Heme biosynthesis
Gene Ontology:
Molecular function: 5-aminolevulinate synthase activity; protein binding; pyridoxal phosphate binding; transferase activity
Biological process: heme B biosynthetic process; response to hypoxia; erythrocyte differentiation; heme biosynthetic process; hemoglobin biosynthetic process; intracellular iron ion homeostasis; intracellular oxygen homeostasis; porphyrin-containing compound metabolic process; tetrapyrrole biosynthetic process
Cellular component: mitochondrial inner membrane; mitochondrion; mitochondrial matrix
Gene-disease validity (ClinGen):
ClinGen rates the evidence that ALAS2 causes each of these diseases.
X-linked erythropoietic protoporphyria (X-linked): Definitive. An erythropoietic protoporphyria in which the cause of the disease is a hemizygous, heterozygous, or homozygous (rare) gain-of-function (GOF) variant (X-linked inheritance pattern) in the terminal regulatory exon of ALAS2.
Homologues: Orthologues: chimpanzee ALAS2 (99% identical), macaque ALAS2 (98% identical), rabbit ALAS2 (94% identical), pig ALAS2 (93% identical), dog ALAS2 (92% identical), mouse Alas2 (90% identical), guinea pig ALAS2 (90% identical), rat Alas2 (89% identical), tropical clawed frog alas2 (68% identical), zebrafish alas2 (65% identical), Drosophila melanogaster Alas (48% identical). Paralogues in human: ALAS1 (61% identical), GCAT (23% identical), SPTLC3 (22% identical), SPTLC2 (21% identical), SPTLC1 (16% identical).
Diseases named in the same sentence as ALAS2 in open-access papers:
ALAS2 is named in the same sentence as 70 diseases in open-access papers, as found by Europe PMC text mining. Sharing a sentence is not in itself a finding about the gene and the disease. The quoted sentences say what the papers report.
X-linked sideroblastic anemia (24 papers, 2013 to 2025). "It is noteworthy that, in humans, a common ALAS2 deficiency, X-linked sideroblastic anemia (XLSA), has ring sideroblasts, erythroblasts accumulating iron in mitochondria, due to impaired heme production." (PMID 40868906, 2025). "In conclusion, we report a novel 11-bp deletion in exon 11 causing a frameshift in the C-terminal of the ALAS2 gene leading to X-linked sideroblastic anemia XLSA phenotype." (PMID 39995829, 2024). "ALAS2 has been targeted for treatment of X-linked sideroblastic anemia, although its broader application as a drug target is currently limited." (PMID 37845713, 2023). "The ALAS2 amino acid mutations that cause X-linked sideroblastic anemia (XLSA, OMIM 300751) are widely dispersed throughout the structure rather than being localized in one region." (PMID 35093382, 2022). "Debilitating and painful diseases such as X-linked sideroblastic anemia and X-linked protoporphyria can result from one of more than 91 genetic mutations in the human erythroid-specific enzyme ALAS2." (PMID 35093382, 2022). "X-linked sideroblastic anaemia (XLSA) is commonly due to mutations in the ALAS2 gene and predominantly affects hemizygous males." (PMID 34930268, 2021). "For example, mutations in ALAS2, the first enzyme of the heme biosynthesis pathway, cause x-linked sideroblastic anemia due to a reduction in the synthesis of PPIX (protoporphyrin IX)." (PMID 34946818, 2021). "P23 carried a heterozygous ALAS2 promoter variation (c.-258C > G), which had previously been reported as a cause of X-linked sideroblastic anemia (MIM 300751)." (PMID 32641076, 2020). "The 5-aminolevulinate synthase (HEM1) is involved in heme biosynthesis and is homologous to human ALAS2, and its mutation causes X-linked sideroblastic anemia." (PMID 31597940, 2019). "Intriguingly, the most common congenital sideroblastic anemia (X-linked sideroblastic anemia) results from an ALAS2 mutation." (PMID 25428262, 2015). "The most common form of CSA is XLSA (X-linked sideroblastic anemia), which is attributed to mutations in the X-linked gene ALAS2." (PMID 26557657, 2015). "ALAS2 encodes 5-aminolevulinate synthase, the rate-controlling enzyme of erythroid heme synthesis; mutations of this gene are the causative of the X-linked sideroblastic anemia in human." (PMID 25975375, 2015). "Of 14 CSA for which DNA was available for genetic analysis, 10 cases were diagnosed as X-linked sideroblastic anemia due to ALAS2 gene mutation." (PMID 22983749, 2013). "The ALAS2 gene instructs the production of the 5'-aminolevulinate synthase 2 enzyme, essential for initiating heme biosynthesis in red blood cells, with mutations linked to X-linked sideroblastic anemia." (PMID 37845713, 2023). "X-linked sideroblastic anemia due to mutations in the ALAS2 gene is the most common congenital form, which may respond favorably to pyridoxine treatment." (PMID 35885655, 2022). "Interestingly, Alas2 is an enzyme localized in the mitochondria of erythrocytes; it regulates the heme biosynthetic pathway and is implicated in X-linked sideroblastic anemia (XLSA)." (PMID 35321029, 2022). "Mutations in ALAS2 may be related to porphyria and X-linked sideroblastic anemia." (PMID 34435051, 2021). "Genetic mutations in human erythroid-specific ALAS (ALAS2) are associated with two inherited blood disorders, X-linked sideroblastic anemia (XLSA) and X-linked protoporphyria (XLPP)." (PMID 29958424, 2018). "The most common form of CSA is X-linked sideroblastic anemia (XLSA), which is caused by mutation of erythroid-specific 5-aminolevulinate synthase (ALAS2), the first enzyme of heme synthesis in erythroid cells." (PMID 22983749, 2013). "The most common disorder is X-linked sideroblastic anemia (XLSA), caused by mutations in 5-aminolevulinic acid synthetase 2 (ALAS2), the initial rate-limiting step in erythroid heme synthesis." (PMID 40052109, 2025).
X-linked sideroblastic anemia (continued). "The most common cause of CSA is X-linked sideroblastic anemia (XLSA) (OMIM: 300752), which is caused by mutations of the erythroid-specific delta-aminolevulinate synthase gene (5′-aminolevulinate synthase 2; ALAS2) located at Xp 11.21." (PMID 39995829, 2024). "We report a case of severe anemia caused by complex hereditary spherocytosis (HS) and X-linked sideroblastic anemia (XLSA) with two mutations in the spectrin beta (SPTB) and 5-aminolevulinic acid synthase (ALAS2) genes." (PMID 36902777, 2023). "The most prevalent form of CSA is X-linked sideroblastic anemia (XLSA), which is attributed to mutations in the X-linked erythroid-specific ALAS2 gene, which encodes the first rate-limiting enzyme in heme biosynthesis." (PMID 36028755, 2022). "X-linked sideroblastic anemia (XLSA) is the most common form of congenital sideroblastic anemia (CSA), and is associated with the mutations in the 5-aminolevulinate synthase 2 (ALAS2)." (PMID 33858445, 2021). "X-linked sideroblastic anemia (XLSA) is the most common form of CSA, and is attributed to the 5-aminolevulinate synthase (ALAS2) mutations." (PMID 33858445, 2021). "Mutations in human ALAS2 yielding diminished ALAS activity or “loss-of-function” are associated with X-linked sideroblastic anemia (XLSA; MIM 300751), while “gain-of-function” ALAS2 mutations are present in X-linked protoporphyria (XLPP; MIM 300752)." (PMID 29958424, 2018). "ALAS2 is not extensively used as a clinical biomarker, except as a biomarker and therapeutic target for X-linked sideroblastic anemia." (PMID 37845713, 2023). "Finally, NGS analysis allowed the diagnosis of X-linked sideroblastic anemia (XLSA) in a woman affected by unexplained macrocytic anemia since birth (case 49-1, ALAS2 mutation p.H524R)." (PMID 34093240, 2021). "ALAS2, given its fundamental role in heme biosynthesis, could potentially serve as a biomarker for conditions such as X-linked sideroblastic anemia, but it is not typically utilized as a blood transcriptional biomarker." (PMID 37845713, 2023).
anemia (18 papers, 2014 to 2025). A reduction in the number of red blood cells, the amount of hemoglobin, and/or the volume of packed red blood cells. "ALAS2+/− female mice, which carry a heterozygous loss-of-function allele on the X chromosome, exhibit microcytic hypochromic anemia due to a reduced hemoglobinization of erythrocytes." (PMID 40868906, 2025). "We report the first case of fetal anaemia in a female fetus where genetic analysis confirmed heterozygosity for an ALAS2 gene mutation causing X-linked CSA." (PMID 34930268, 2021). "A former study demonstrated that ALAS2 mutation causes severe anemia mechanistically by arresting erythroid differentiation at the proerythroblast stage due to heme insufficiency." (PMID 34258471, 2021). "Anemia due to the ALAS2 Arg368Trp variant responds to pyridoxine supplements." (PMID 39281190, 2024). "We also evaluated genes associated with mitochondrial function (Abcb7, Alas2, and Sod2), which may possibly explain the anemia phenotype in Sf3b1+/− mice." (PMID 25481243, 2014). "Hemizygous variants in ABCB7, ALAS2, and MAGED2, associated with X-linked recessive disorders (sideroblastic anemia and antenatal Bartter syndrome), can manifest with hydrops or anemia in utero in affected males." (PMID 41256177, 2025). "The co-inheritance of a GATA1 G208R with an ALAS2 R479Q led to a shift of the GATA1-typical anemia towards a sideroblastic anemia with macrothrombocytopenia." (PMID 36231035, 2022). "Previous studies have shown that ALAS2 mutations prevent RBC differentiation due to haem deficiency during the proerythrocyte phase, thereby causing severe anaemia." (PMID 35138035, 2022). "Defects in ALAS2 result in decreased protoporphyrin synthesis and subsequent reductions in iron incorporation and heme synthesis, leading to microcytic anemia and the appearance of ring sideroblasts in the bone marrow." (PMID 26557657, 2015). "Male mice lacking ALAS2, which is linked to the X-chromosome, die by embryonic day ~11.5 due to severe anemia." (PMID 40868906, 2025). "Additionally, ALAS2 heterozygosity (ALAS2+/−) leads to impaired erythropoiesis, resulting in anemia and ineffective iron utilization." (PMID 40868906, 2025). "Our report is novel in that there are no previous cases in the literature of anaemia in a female fetus heterozygous for ALAS2 mutation." (PMID 34930268, 2021). "Initial screening using a rare anaemia panel did not identify a pathogenic ALAS2 mutation." (PMID 40391332, 2025). "Other relevant findings include the low overall expression of membrane genes and genes involved in erythropoiesis (GATA1, ALAS2, ABCB10, and HEMGN) in CSA and overexpression in the rest of the congenital anemias studied compared to healthy controls." (PMID 39519257, 2024). "Without ALAS2, yolk sac erythroblasts cannot synthesize hemoglobin, leading to fatal anemia in mid-gestation." (PMID 40868906, 2025). "In severely affected females, macrocytic erythroid cells with the non-functional ALAS2 enzyme fail to develop into viable erythrocytes and are released at an accelerated rate into the circulation in response to anaemia." (PMID 34930268, 2021). "Anemia in many XLSA patients responds variably to supplementation with pyridoxine (vitamin B6) which is converted into pyridoxal 5‐phosphate (PLP), the active cofactor essential for ALAS2 activity." (PMID 27247955, 2016).
sideroblastic anemia (18 papers, 2009 to 2025). "In this study, we describe a novel mutation in the C-terminal of the ALAS2 gene in a man, in his late twenties, who was incidentally detected and diagnosed to have an X-linked sideroblastic anemia phenotype." (PMID 39995829, 2024). "Some of these variants result in increased ALAS2 activity causing X-linked protoporphyria and other variants have diminished ALAS2 activity causing sideroblastic anemia." (PMID 35806474, 2022). "ALAS2 mutation is usually associated with sideroblastic anemia, iron overload, and X-linked macrocytic erythropoietic anemia in women." (PMID 35204186, 2022). "The remaining new variants were identified in enzyme genes (PKLR: p.R531S; HK1: p.R12X, p.G451R; NT5C3A: p.R22X), and in genes associated with sitosterolemia (ABCG5: p.Y458X) and sideroblastic anemia (ALAS2: p.H524R)." (PMID 34093240, 2021). "In those cases, as here, the mutation has little effect on ALAS2 catalytic activity, but results in sideroblastic anemia in vivo." (PMID 30678654, 2019). "In contrast, NSG data from one congenital sideroblastic anaemia patient carrying an ALAS2 mutation and other healthy donors showed a multi-lineage engraftment with high a percentage of the lymphoid/myeloid cell ratio." (PMID 26643973, 2015). "Mutations in ALAS2 gene cause insufficient heme production, mitochondria iron overload, and oxidative stress, as observed in sideroblastic anemia." (PMID 24782769, 2014). "Sideroblastic anemia is a rare X-linked disease, which is caused by the defect in the erythroid-specific enzyme 5-aminolevulinic acid synthase-2 (ALAS2)." (PMID 24633395, 2014). "Mutations in the ALAS2 gene are responsible for the most common form of inherited sideroblastic anemia, named X-linked sideroblastic anemia (XLSA; OMIM: #300751)." (PMID 24782769, 2014). "This novel mechanism of ALAS2 may result in the identification of mutations that result in idiopathic sideroblastic anemias or iron refractory anemias." (PMID 35806474, 2022). "Variants in the ALAS2 gene, encoding ALAS2 (regulated by CLPX) can cause hereditary sideroblastic anemia in humans." (PMID 41300811, 2025). "The most common hereditary sideroblastic anemia is the x-linked SA (MIM #300751), caused by mutations of the mitochondrial enzyme delta-aminolevulinate synthase 2 (ALAS2), while recessive forms are associated with mutations in mitochondrial transport proteins." (PMID 36986429, 2023). "The activation of IRPs determines the translational repression of ALAS2 resulting in sideroblastic anemia." (PMID 24782769, 2014). "Genetic analysis of potentially causative genes such as ALAS-2 was performed, but all results were negative, ruling out hereditary sideroblastic anemia." (PMID 40655904, 2025). "Congenital sideroblastic anemias are caused by defects in the early steps in heme synthesis, including those encoding the human homologs of yeast HEM25 (SLC25A38 in humans) and HEM1 (ALAS2 in humans)." (PMID 28404662, 2017). "Herein, we report a novel 11-bp deletion in exon 11 leading to a frameshift in the C-terminal region of the ALAS2 gene with a non-functional longer polypeptide of 614 amino acids leading to a loss-of-function mutation manifested as an X-linked sideroblastic anemia phenotype." (PMID 39995829, 2024).
congenital sideroblastic anemia (10 papers, 2015 to 2024). "In SF3B1K700E expressing cells, ABCB7 and ALAS2, known causative genes for congenital sideroblastic anemia, were downregulated." (PMID 36028755, 2022). "The most frequent non-syndromic congenital sideroblastic anemia is caused by mutations in the ALA synthase gene (ALAS2)." (PMID 35885655, 2022). "X-linked sideroblastic anemia (XLSA), the most common form of congenital sideroblastic anemia, is caused by a germline mutation in the erythroid-specific 5-aminolevulinate synthase (ALAS2) gene." (PMID 35637209, 2022). "Congenital sideroblastic anemia (CSA) is most frequently caused by X-linked mutations in ALAS2 (Delta-aminolevulinate synthase 2, XLSA), followed by ABCB7 (ATP Binding Cassette Subfamily B Member 7), SLC25A28 (Solute Carrier Family 25 Member 28) and GLRX5 (Glutaredoxin 5)." (PMID 33672223, 2021). "ALAS2 mRNA is weakly expressed in bone marrow erythrocytes of patients with congenital sideroblastic anemia." (PMID 35204186, 2022). "According to recent human genetics findings, mutations in FECH, ALAS2, and CLPX underlie most cases of the disorder erythropoietic protoporphyria, while mutations in ALAS2 and in the mitochondrial glycine transporter SLC25A38 are the most frequent causes of congenital sideroblastic anemia." (PMID 38927630, 2024).
erythropoietic protoporphyria (9 papers, 2014 to 2025). A rare congenital metabolic disorder characterized by an inborn error of porphyrin-heme biosynthesis. "Although mutations in ClpX also lead to the blood disorder erythropoietic protoporphyria, the role of the human ALAS2-ClpX interaction is still being elucidated." (PMID 35093382, 2022). "However, in any of the protoporphyrias, pathological variants in the ALAS2, CLPX or FECH genes lead to the accumulation of excess PPIX in the maturating erythroblasts in the bone marrow." (PMID 39011756, 2025). "Human ALAS2 variants with higher than normal activity are now known to occur in nature, and are associated with a form of erythropoietic protoporphyria known as X-linked dominant protoporphyria, which is characterized by a 24-fold increase in erythrocyte PPIX concentrations." (PMID 24718052, 2014). "The role of iron in mitigating erythropoietic porphyrias is further underlined by the description of a patient with erythropoietic protoporphyria caused by combination of mutations in CLPX and in the IRE domain of ALAS2." (PMID 34940556, 2021). "Gain-of-function mutations in ALAS2, the first enzyme of erythroid heme synthesis, cause X-linked dominant protoporphyria (XLPP) in approximatively 4–10% of the patients with erythropoietic protoporphyria." (PMID 34940556, 2021). "Additionally, we explored whether cimetidine modulates ALAS2 activity in vitro and then in murine bone marrow cells, as cimetidine also has been proposed to be an effective treatment for erythropoietic protoporphyria (EPP)." (PMID 38254627, 2023). "Erythropoietic protoporphyria (EPP) and X-linked protoporphyria (XLP) are inherited disorders resulting from defects in two different enzymes of the heme biosynthetic pathway, i.e., ferrochelatase (FECH) and delta-aminolevulinic acid synthase-2 (ALAS2), respectively." (PMID 35054318, 2022). "In erythropoietic protoporphyria (EPP), sun exposure leads to skin photosensitivity due to the overproduction of photoreactive porphyrins in bone marrow erythroid cells, where heme synthesis is primarily driven by the ALAS2 isozyme." (PMID 38254627, 2023).